HK2 (hexokinase 2)
Diseases named in the same sentence as HK2 in open-access papers (continued):
Sharing a sentence is not in itself a finding about the gene and the disease.
ovarian carcinoma (continued). "HIF-1α also induces invasion and metastasis of ovarian cancer cells through the activation of the rate-limiting enzymes of the glycolysis pathway, hexokinase 2 and phosphofructokinase, to promote the Warburg effect." (PMID 36230617, 2022). "The positive expression of HK2 had observed in ovarian cancer cell lines, OVCA433, A2780 and SKOV3, by using immunocytochemistry and western blotting." (PMID 35711830, 2022). "In this study, alteration of HK2 expression in human ovarian cancer cells affected the protein level of Akt1 and p-Akt1, suggesting that there should had a potential interaction relationship between HK2 and Akt1/p-Akt1 during human ovarian cancer progress." (PMID 35953860, 2022). "NO generated by NOS can improve the Warburg effect by upregulating hexokinase 2 (HK2) expression in ovarian cancer cells." (PMID 35326412, 2022). "The positive correlation between HK2 and β-catenin, c-myc, CyclinD1 in human ovarian cancer were confirmed from the GEPIA online database." (PMID 35711830, 2022). "Consistently, the increased HK2 expression also observed in human ovarian carcinoma tissues in this study." (PMID 35711830, 2022). "All of these results demonstrate that exogenously expressed HK2 in human ovarian cancer cells significantly enhances cell migratory and invasive capacity in vitro." (PMID 35953860, 2022). "In this study, elevation of HK2 in human ovarian cancer cells significantly promoted cell growth and motility capacity, and further study implied that active of Akt1 in HK2-modified cells must associated with the enhanced cell proliferation and motility." (PMID 35953860, 2022). "When ovarian cancer cells are exposed to chronic hypoxia, HK2 expression increases to levels similar to that of multidrug-resistant cells." (PMID 36230617, 2022). "All of these results revealed the promotive effect of HK2 on regulating cell proliferation and tumor formation in ovarian cancer, which consistent with other cancers." (PMID 35711830, 2022). "In ovarian cancer cells, overexpressing of HK2 enhanced cell motility by inducing of EMT-related proteins, such as CDH2, fibronectin, MMP9, ZEB1, ZEB2 and vimentin." (PMID 35953860, 2022). "NK007, a (±)‐tylophorine malate obtained from the Asclepiadaceae family, suppresses the proliferation of PTX-resistant ovarian cancer cells by reducing HK2-mediated glycolysis." (PMID 36339566, 2022). "HK2 was further observed to regulate ovarian cancer metastasis and stemness via FAK/ERK1/2 signaling pathway-mediated MMP9/NANOG/SOX9 expression." (PMID 35711830, 2022). "SIK2 upregulates the expression level of HIF-1α, which enhances the transcription of glycolysis-associated genes (HK2 and PFKL), inducing the metastasis and invasion of ovarian cancer." (PMID 35004308, 2021). "Combined with our previous studies, we clarified that miR-145 targeted HK2 to inhibit the Warburg effect of ovarian cancer cells, and revealed that berberine/miR-145/HK2 plays an important role in the Warburg effect of ovarian cancer cells." (PMID 33391417, 2021). "Our previous studies have confirmed that miR-145 inhibits Warburg effect by targeting HK2 in ovarian cancer cells." (PMID 33391417, 2021). "The study provided the new mechanistic evidence about TET3/miR-145/HK2 pathway in the anti-Warburg effect of berberine, providing evidence for berberine to become a candidate drug for clinical treatment of ovarian cancer." (PMID 33391417, 2021). "It was previously found that compared to ovarian cancer cells, the expression of HK2 in cisplatin-resistant ovarian cancer cells increases." (PMID 33802591, 2021). "We found that PGC1α regulates mitochondrial apoptosis and glycolysis through the HSP70/HK2 pathway to promote cisplatin resistance in ovarian cancer cells." (PMID 33802591, 2021). "The regulatory mechanism of berberine/TET3/miR-145/HK2 pathway in the Warburg effect of ovarian cancer cells provides potential therapeutic targets in treatment of ovarian cancer." (PMID 33391417, 2021).
ovarian carcinoma (continued). "Kaplan-Meier plotter analysis indicated that among the highly expressed glycolysis genes, SLC16A3, HK2, GPI, PFKP, and PGK1, were closely associated with poor PFS, PPS, or OS in patients with ovarian cancer." (PMID 34277429, 2021). "and found that when the UBA domain is knocked out, the mitochondrial localisation of parkin and HK2 increased, and then found that ovarian cancer cell mitophagy increased, which decreases the drug sensitivity to cisplatin." (PMID 33924293, 2021). "It suggests that the location of parkin and HK2 in cells will affect the physiological process of mitochondria, that is, mitophagy, and then affect the prognosis of ovarian cancer." (PMID 33924293, 2021). "High HK2 expression in ovarian cancer was an independent predictor of disease-free survival (DFS) as confirmed in the literature." (PMID 34277429, 2021). "The majority of cell lines expressed more HK1 transcripts than HK2 (HK1:HK2 ratio 2.3 ± 0.4), and the levels of HK transcripts correlated with one another, which we further confirmed for selected three ovarian cancer cell lines at the protein level." (PMID 34895333, 2021). "Inhibition or knockdown of HK2 significantly attenuated tumor growth and the dissemination of ovarian cancer xenografts." (PMID 33160373, 2020). "HK2 overexpression has been observed in high-grade and advanced ovarian cancer and is correlated with early recurrence and short progression-free survival in ovarian cancer patients." (PMID 33160373, 2020). "Several key glycolytic enzymes, comprising HK2, PFK, and PKM2, are highly expressed in ovarian cancer cells and were implicated in anti-apoptotic and cell survival processes which correlate with chemo-resistance." (PMID 32211323, 2020). "Hexokinase-2 (HK2), the first glycolytic rate-limiting enzyme, shows limited expression in normal adult tissues but is overexpressed in many tumor tissues, including ovarian cancer." (PMID 33160373, 2020). "The HK2 immunoreactivity in ovarian cancers was significantly higher than in benign cystadenomas (p < 0.001)." (PMID 31212816, 2019). "Lysophosphatidic acid, a blood-borne lipid mediator that is elevated in the ascites of ovarian cancer patients, has been shown to up-regulate HK2 and glycolysis, leading to enhanced proliferation of ovarian cancer cells." (PMID 31212816, 2019). "Our findings revealed higher HK2 expression in ovarian cancer, which was correlated with shorter overall and disease-free survival." (PMID 31212816, 2019). "A recent study also revealed that HK2 contributes to ovarian cancer cisplatin resistance by regulating cisplatin-induced, ERK-mediated autophagy." (PMID 31212816, 2019). "In conclusion, HK2, which is regulated by the tumor microenvironment, controls lactate production and contributes to ovarian cancer metastasis and stemness regulation via FAK/ERK1/2 signaling pathway-mediated MMP9/NANOG/SOX9 expression." (PMID 31212816, 2019). "Here, we demonstrated that HK2 was overexpressed in ovarian cancer and displayed significantly higher expression in ascites and metastatic foci." (PMID 31212816, 2019). "Taken together, this study reveals that HK2 is a potentially useful molecular prognostic marker and a therapeutic target for ovarian cancer." (PMID 31212816, 2019). "GEPIA further revealed a significant clinical correlation between MMP9, uPA, and VEGF and HK2 expression (p < 0.05) in ovarian cancer clinical samples." (PMID 31212816, 2019). "GEPIA further revealed a significant clinical correlation between NANOG, OCT4, KLF4, SOX9, and CD117 and HK2 expression (p < 0.05) in ovarian cancer clinical samples." (PMID 31212816, 2019). "Since G6P—the product formed by HKs—was higher in metastatic ovarian cancers when compared to normal ovarian tissue and primary ovarian cancers, a role for HK2 in ovarian cancer metastasis is suggested." (PMID 31212816, 2019).
ovarian carcinoma (continued). "By immunohistochemistry, moderate to strong HK2 protein was localized in the cytoplasm in ovarian cancer samples; in contrast, it was barely detectable in benign cystadenomas." (PMID 31212816, 2019). "Given that metastasis is one of the characteristics of CSCs, we investigated the effects of HK2 on sphere-forming abilities and changes to CSC-related genes in ovarian cancer cell lines following HK2 manipulation." (PMID 31212816, 2019). "Our data also showed a blockage of metastasis and sphere formation by 2-DG in vitro, suggesting the activity of HK2 is essential for its metastasis and stemness effects in ovarian cancer." (PMID 31212816, 2019). "In this study, we focused not only on the clinical significance, but also on the functional roles and downstream mechanisms of HK2 in ovarian cancer." (PMID 31212816, 2019). "Our in vitro and in vivo findings demonstrate that HK2 is overexpressed in ovarian cancer, ascites and metastatic foci." (PMID 31212816, 2019). "By western blot analysis, we found an up-regulation of HK2 protein expression in ovarian cancer cell lines (OVCAR-3, OVCA429, OVCA433, OC316, ES-2, TOV21G, A2780S, and A2780CP), compared to normal ovarian epithelial cell lines (HOSE 6-3 and HOSE 11-12)." (PMID 31212816, 2019). "It demonstrated that 20(S)-Rg3 inhibited the Warburg effect by targeting STAT3/HK2 pathway in ovarian cancer cells." (PMID 30514289, 2018). "We also compared the expression levels of STAT3, SITR3, HIF‐1α, GLUT1, LDHA, and HK2 of 44 ovarian cancer patient serums with 35 normal controls." (PMID 30094960, 2018). "We tested the expression levels of STAT3, SITR3, HIF‐1α, GLUT1, LDHA, and HK2 in 38 ovarian cancer patient tissues and 22 normal tissues." (PMID 30094960, 2018). "STAT3 has been revealed to potentiate glucose metabolism and accelerate glycolysis by upregulating HK2 in breast, bladder, and ovarian cancer cells." (PMID 28445971, 2017). "Here, we report that miR-29b negatively regulates AKT2/AKT3 expression, causing HK2/PKM2 downregulation and leading to a decreased Warburg effect and slowed ovarian cancer progression." (PMID 26512921, 2015). "Further research revealed that HK2 is essential for the development of ovarian cancer." (PMID 40868085, 2025). "Also, Kaplan–Meier analysis demonstrated that increased HK2 expression was related to shortened progression‐free survival of patients with ovarian cancer." (PMID 39114948, 2024). "We found various expressions of HK1 and HK2 mRNA and protein levels in ovarian cancer cells." (PMID 39114948, 2024). "Among the HK isoforms, HK2, the most active isozyme, is markedly expressed in cancer cells, and its expression is related to the progression of and poor prognosis for glioblastoma and epithelial ovarian cancer." (PMID 39114948, 2024). "To determine whether treatment with GP‐2250 affects upstream metabolites of glycolysis, we examined HK1 and HK2 mRNA and protein expression and activity levels in ovarian cancer cell lines." (PMID 39114948, 2024). "The overexpression of HK2 in ovarian cancer leads to resistance against chemotherapy." (PMID 38577616, 2024). "Moreover, mutations in the ubiquitin-associated domain of p62 have been found to alter the sensitivity of ovarian cancer cells to cisplatin by promoting mitophagy through the localization of hexokinase 2 in mitochondria." (PMID 38038814, 2023). "In addition, SPARC shows dose-dependent inhibition of HK2 activity and decreased mitochondrial activity on human and mouse ovarian cancer cell lines, which is related to the energy metabolism of tumor metastasis." (PMID 38076208, 2023). "In conclusion, this study demonstrated that HK2 could promote cell proliferation and tumor formation by inducing c-myc and CyclinD1 expression through Wnt/β-catenin signaling pathway in ovarian cancer cells." (PMID 35711830, 2022).
ovarian carcinoma (continued). "And the positive rate of HK2 was increased from 28.60% (normal ovarian samples, 6/21) to 52.80% (well differentiated epithelial ovarian cancer samples, 19/36) and 77.00% (37/48) in poorly differentiated epithelial ovarian cancer samples." (PMID 35711830, 2022). "Moreover, soft agar assay for colony formation was performed to further confirm the biological role of HK2 on regulating the cell proliferation in human ovarian cancer cells." (PMID 35711830, 2022). "Moreover, the activation of Wnt/β-catenin signaling pathway was observed in HK2 overexpressed ovarian cancers." (PMID 35711830, 2022). "Hexokinase 2 (HK2) is highly expressed in ascites and metastases in patients with ovarian cancer." (PMID 36407100, 2022). "This might be due to NANOG promotes the occurrence and stemness of ovarian cancer via glycolytic enzyme HK2 in ovarian cancer." (PMID 35022030, 2022). "All of these results suggested that HK2 expression was stimulated in ovarian carcinoma tissues and might be involved in the process of ovarian carcinogenesis." (PMID 35711830, 2022). "Additionally, the positive correlation between HK2 and β-catenin, c-myc, CyclinD1 in human ovarian cancer were confirmed from the GEPIA online database (p<0.05)." (PMID 35711830, 2022). "β-Escin is a natural pentacyclic triterpenoid saponin derived from the seed of Aesculus hippocastanum L. It has been found in studies to limit the lowering of HIF-1α-targeted proteins, LDHA, CD31, and HK2 in ovarian cancer (OvCa) mouse omentum, therefore inhibiting OvCa invasion." (PMID 36339566, 2022). "In our study, exogenous HK2 was stably over expressed in ovarian cancer cells." (PMID 35711830, 2022). "In order to determine whether the Akt1 and p-Akt1 expression could be regulated under HK2 expression in human ovarian cancer cell lines, western blot was used to detected the protein levels of Akt1 and p-Akt1 in HK2- modified human ovarian cancer cells." (PMID 35953860, 2022). "In this study, further study also demonstrated that HK2 could elevate the expression of EMT-related factors in human ovarian cancer cell, like fibronectin, MMP9, CHD2, Vemintin, ZEB1 and ZEB2." (PMID 35953860, 2022). "Moreover, overexpressing of HK2 promoted cell growth by reducing p21 and p27 expression in ovarian cancer cells." (PMID 35953860, 2022). "However, the potential function of HK2 on regulating cell proliferation and motility in human ovarian cancer cells was still less to known." (PMID 35953860, 2022). "Therefore, we evaluated the interaction between PGC1α and HK2 in ovarian cancer cisplatin-resistant cells." (PMID 33802591, 2021). "Moreover, Hexokinase 2 regulates the metastasis, invasion, and cell stemness of ovarian cancer cells through the FAK/ERK1/2/MMP9/NANOG/SOX9 signal transduction pathways." (PMID 34596006, 2021). "Therefore, p62 serves as an important autophagy receptor of HK2 in ovarian cancer cells and participates in the degradation of HK2." (PMID 33924293, 2021). "Our previous results confirmed that miR-145 could target HK2 to inhibit the Warburg effect of ovarian cancer cells." (PMID 33391417, 2021). "In conclusion, berberine could inhibit the expression of HK2 through miR-145, thus inhibiting the Warburg effect of ovarian cancer cells." (PMID 33391417, 2021). "Clinical, in vitro and in vivo evidence strongly suggested that upregulation of HK2 in ovarian cancer was correlated with metastasis and poor survival and mediated migration, invasion and stemness via PTK2/MAPK1/3/MMP9/NANOG/SOX9 signaling cascades in vitro and in a nude mouse model." (PMID 33052246, 2020). "HK2 has been shown to be correlated with the progression and chemoresistance of ovarian cancer and could be a therapeutic target." (PMID 33160373, 2020). "However, the roles of HK2 inhibition in chemoresistant ovarian cancer need to be further elucidated." (PMID 33160373, 2020).
ovarian carcinoma (continued). "Moreover, knockdown of HK2 in ovarian cancer cells attenuated lactate production, cell invasion, and cancer cell stemness." (PMID 33520999, 2020). "In conclusion, we describe in this study the overexpression of HK2 in ovarian cancer." (PMID 31212816, 2019). "Furthermore, a recent study showed that HK-2 (hexokinase-2), a key enzyme of the rate-limiting step in glycolysis up-regulates cisplatin-resistance in ovarian cancer cells by enhancing cisplatin-induced autophagy." (PMID 31122265, 2019). "Functionally, knockdown of HK2 in ovarian cancer cell lines and ascites-derived tumor cells hindered lactate production, cell migration and invasion, and cell stemness properties, along with reduced FAK/ERK1/2 activation and metastasis- and stemness-related genes." (PMID 31212816, 2019). "We next determined whether the glucose analog 2-DG, an inhibitor of glycolysis, was able to mimic the effects of HK2 silencing in ovarian cancer cells." (PMID 31212816, 2019). "Similarly, the overexpression of the glycolityc pace-maker enzyme hexokinase 2 (HK2) mediates the resistance to cisplatin in ovarian cancer by favoring the activation of ERK." (PMID 31117237, 2019). "In this study, we found that CAF-CM up-regulates HK2 in ovarian cancer." (PMID 31212816, 2019). "Besides NANOG and SOX9, we also revealed an up-regulation of OCT4, KLF4, and CD117 by HK2 in ovarian cancer, which further supports the concept that HK2 regulates CSCs." (PMID 31212816, 2019). "HK2 is a predominant isoform of HK, which is upregulated in ovarian cancer." (PMID 30514289, 2018). "In addition, PGC1α promoted cisplatin resistance by modulating the HSP70/HK2/VDAC1 signaling pathway, affecting the binding of HK2 to VDAC1, causing alterations in mitochondrial membrane potential, and reducing the apoptosis of ovarian cancer cells." (PMID 38711526, 2024). "However, the HK2 isoform is the critical regulator of the Warburg effect in many cancer types, viz prostate, hepatocellular, gliomas, breast, gastrointestinal, lung and ovarian cancers, making it an important therapeutic target against cancer." (PMID 35216429, 2022). "As shown in this study, HK2 overexpression could activate Wnt/β-catenin pathway by up-regulating β-catenin expression, further promoting cell proliferation and tumor formation by inducing c-myc and Cyclin D1 expression in ovarian cancer cells." (PMID 35711830, 2022). "This study demonstrated that HK2 could induce EMT-related proteins and reduce cell cycle inhibitor by activating Akt1 in human ovarian cancer cells, subsequently enhancing cell motility and growth, suggesting that HK2 participate in the malignant process of ovarian cancer by interacting with Akt1." (PMID 35953860, 2022). "Therefore, PGC1α may promote cisplatin sensitivity of ovarian cancer cells through the HSP70/HK2/VDAC1 signaling pathway." (PMID 33802591, 2021). "In hypoxic ovarian cancer cells, FV-429 can interfere with the expression and phosphorylation of c-Scr, inhibit the translocation and DNA binding activity of STAT3, and inhibit HIF-1α expression, causing the downregulation of HK2 and VEGF and enhancement of the G2/M arrest induced by paclitaxel." (PMID 35004308, 2021). "This drug delivery strategy could be used for the selective inhibition of HK2 in ovarian cancer." (PMID 33160373, 2020). "Moreover, knockdown of HK2 resulted in lower lactate production in ovarian cancer cells." (PMID 31212816, 2019). "HK2 could be a potential prognostic marker and therapeutic target for ovarian cancer." (PMID 31212816, 2019). "Moreover, we show that IL-6, but not IL-8, is one of the major cytokines in CAF-CM that contributes to HK2 up-regulation through binding of IL-6R in ovarian cancer cells, suggesting that HK2 expression can be regulated by the tumor microenvironment in ovarian cancer." (PMID 31212816, 2019).